COMETT (cytosolic oncogenic antisense to MET transcript)
Synonyms: COMET; formerly LINC01510
Gene: Long non-coding RNA gene on chromosome 7 (116,563,594 to 116,724,495, reverse strand). Ensembl gene ENSG00000231210.
Diseases named in the same sentence as COMETT in open-access papers:
COMETT is named in the same sentence as 6 diseases in open-access papers, as found by Europe PMC text mining. Sharing a sentence is not in itself a finding about the gene and the disease. The quoted sentences say what the papers report.
tumor (3 papers, 2019 to 2021). "Furthermore, they found that COMETT acted as a tumor suppressor in ccRCC tumorigenesis by inhibiting Wnt/β-catenin signaling." (PMID 34386428, 2021). "Similarly, the repression of COMETT markedly reduces the viability and proliferation of tumor cells harboring BRAF mutation or RET oncogene rearrangement, as well as the motility and invasiveness of tumor cells in vitro." (PMID 33142861, 2020). "Of note, COMETT depletion significantly impairs the expression levels of different MAPK pathway effectors, including—but not limited to—the MET oncogene, also increasing tumor cells’ sensitivity to vemurafenib, a common inhibitor of mutated B-raf." (PMID 33142861, 2020).
COMETT also shares sentences with these, for which no sentence is quoted: colorectal cancer (2 papers); kidney cancer (1); lung carcinoma (1); non-small cell lung carcinoma (1); thyroid cancer (1).